Y_RNA (Y RNA )
Gene: Miscellaneous RNA gene on chromosome 11 (77,691,650 to 77,691,751, forward strand). Ensembl gene ENSG00000206816.
Homologues: Orthologues: chimpanzee Y_RNA (99% identical), macaque Y_RNA (95% identical), guinea pig Y_RNA (88% identical), tropical clawed frog Y_RNA (72% identical). Paralogues in human: Y_RNA (89% identical), RNY3 (88% identical), RNY3P1 (88% identical), Y_RNA (88% identical), Y_RNA (87% identical), Y_RNA (86% identical), RNY3P5 (85% identical), Y_RNA (85% identical), RNY3P11 (84% identical), RNY3P14 (84% identical), Y_RNA (84% identical), Y_RNA (83% identical), and 95 more.